CST3 (cystatin C)
Diseases named in the same sentence as CST3 in open-access papers (continued):
Sharing a sentence is not in itself a finding about the gene and the disease.
chronic kidney disease (continued). "This study aimed to determine and compare the levels of serum cystatin C in patients with chronic kidney disease (stages 1–5) based on creatinine clearance values and association with serum creatinine." (PMID 33401560, 2021). "Glomerular filtration rate (GFR) was calculated by using combined creatinine–cystatin C CKD-EPI (Chronic Kidney Disease Epidemiology Collaboration) equation." (PMID 33430940, 2021). "A previously performed meta-analysis showed that GFR estimated by cystatin C has a better predictive power for mortality and the prognosis of end-stage renal disease than that estimated by creatinine." (PMID 33828483, 2021). "There was a stepwise increase in mean serum cystatin C levels in this group of chronic kidney disease patients." (PMID 33401560, 2021). "Serum cystatin C levels in the 140 chronic kidney disease patients ranged from 0.68 to 8.13 mg/L (normal reference interval 0.61–0.95 mg/L)." (PMID 33401560, 2021). "The highest serum cystatin C levels (4.46 ± 1.34 mg/L) were seen in patients with end stage renal disease (ESRD)." (PMID 33401560, 2021). "The mean serum cystatin C levels from stage 1 to 5 were greater than 1.10 mg/L in this group of chronic kidney disease patients." (PMID 33401560, 2021). "In a later study, baseline serum cystatin C level was a better predictor of end stage renal disease than measured glomerular filtration rate (mGFR) and serum creatinine for predicting end-stage renal disease in type 2 diabetic patients with raised albuminuria." (PMID 33401560, 2021). "Race/ethnicity is found to affect cystatin C levels in the normal population, and the prevalence of chronic kidney disease (CKD) estimated using cystatin C." (PMID 33996155, 2021). "Kidney graft function was estimated with routine parameters (creatinine, urea, cystatin C, and Chronic Kidney Disease Epidemiology Collaboration study equations) and precisely measured using chromium-51 labelled ethylenediaminetetraacetic-acid clearance." (PMID 32764335, 2020). "Using the 90th percentiles of the CV values as a limit for clinical change means that NGAL has to change by 83.3%, KIM1 by 45.5% and Cystatin C by 46.3% before the change can be considered clinically significant in patients with chronic kidney disease." (PMID 32349578, 2020). "The purpose of the work was to study the level of cystatin C, ghrelin and their interaction in patients with early (I-II) stages of chronic kidney disease against the background of obesity." (PMID 33456602, 2020). "Cystatin C (CysC) is considered to be an accurate marker of impaired renal function, especially in the early stages of Chronic Kidney Disease (CKD)." (PMID 33134263, 2020). "The bounds reported by the later study stemmed from different estimation equations for GFR (Chronic Kidney Disease Epidemiology Collaboration cystatin C equation and Full Age Spectrum creatinine equation, respectively)." (PMID 32330140, 2020). "The purpose of our work is to study the level of cystatin C, ghrelin, and their interrelation in patients with early stages (I-II) of chronic kidney disease (CKD) against the background of obesity." (PMID 33456602, 2020). "Estimated glomerular filtration rate was calculated by three equations established by chronic kidney disease epidemiology collaboration (based on creatinine and/or cystatin C)." (PMID 33024521, 2020). "In humans, decreased levels of Prevotella copri and Faecalibacterium prausnitzii populations were observed in severe forms of chronic kidney disease (CKD), which also negatively correlate with the presence of important diagnostic markers, such as C-reactive protein and cystatin C levels." (PMID 32260384, 2020). "We evaluated the error of creatinine and/or cystatin-C based formulas in reflecting real renal function over a wide range of glomerular filtration rate (from advanced chronic kidney disease to hyperfiltration)." (PMID 31561432, 2019).
chronic kidney disease (continued). "Cystatin C has been demonstrated to be a better biomarker to detect early stages of chronic kidney disease than creatinine and eGFR." (PMID 29694626, 2018). "The KDIGO guidelines recommend the estimation of GFR based on serum cystatin C in adult patients with suspected stage G3a of chronic kidney disease (GFR between 45 and 60 ml/min/1.73 m2)." (PMID 30158836, 2018). "A strong correlation between cystatin C concentration and end-stage renal disease was demonstrated in morbidly obese patients." (PMID 30035656, 2018). "Cystatin C is a protein responsible for inhibit cysteine proteases and is a biomarker able to detect early stages of chronic kidney disease." (PMID 29694626, 2018). "Chronic kidney disease (CKD) is associated with increased procoagulants, including cystatin C, C-reactive protein, interleukin-6, tumor necrosis factor-α soluble receptor 1, intercellular adhesion molecule-1, fibrinogen, and factor VIII." (PMID 30115029, 2018). "We estimated glomerular filtration rate from serum creatinine and cystatin C in a cohort of 1,741 mainly older people diagnosed with chronic kidney disease in primary care." (PMID 29016597, 2017). "Rs11574358 was recently identified to be associated with traits related to ageing, including cardiovascular disease prevalence, systolic blood pressure, cancer prevalence, total cholesterol and cystatin C in serum (chronic kidney disease)." (PMID 29064820, 2017). "Recently, new equations such as the Chronic Kidney Disease Epidemiology Collaboration (CKD-EPI) equations based on cystatin C and/or serum creatinine have been recommended for clinical applications." (PMID 28693441, 2017). "Serum biomarkers, such as serum creatinine (SCr) and serum cystatin C (SCysC), have been widely used to evaluate renal function in patients who have chronic kidney disease (CKD)." (PMID 29069842, 2017). "They concluded that the combined serum cystatin C/serum creatinine/blood urea nitrogen (BUN) Chronic Kidney Disease in Children (cKiD) equation estimates the GFR of children with an SFK with superior precision." (PMID 26482253, 2016). "Cystatin C (CysC), a marker for chronic kidney disease, exists as three sequence proteoforms, in addition to the wild-type sequence: one contains hydroxyproline at position 3 (3Pro-OH), the two others have truncated sequences (des-S and des-SSP)." (PMID 36778895, 2016). "At 3 months of age, her cystatin C-estimated glomular filtration rate (eGFR) was 51 mL/min/1.73 m2 and at 5 months it rose to 64 mL/min/1.73 m2, indicating stage 2 chronic kidney disease (CKD)." (PMID 26019888, 2015). "The optimal model used estimated GFR by the Chronic Kidney Disease Epidemiology Collaborative (CKD-EPI) creatinine-cystatin C equation (R2 = 0.580)." (PMID 24887089, 2014). "Using serum cystatin C resulted in widely varying eGFR which significantly affected the classification of chronic kidney disease." (PMID 24868463, 2014). "Moderate to severe chronic kidney disease with a baseline eGFR by CKD-EPIcreatinine-cystatin C of less than 60 mL/min was evident in 20% of patients." (PMID 24887089, 2014). "Serum cystatin C has been shown to be superior to creatinine as a marker of kidney function in chronic kidney disease." (PMID 23327592, 2013). "Sixteen SNPs were selected for replication based on the most promising associations with chronic kidney disease (CKD), estimated glomerular filtration rate (eGFR), and serum cystatin C in FHS." (PMID 18522750, 2008). "Both creatinine-based eGFR and cystatin C correlated with most inflammatory markers in subjects with chronic kidney disease." (PMID 18681974, 2008). "Our findings showed that incorporation of cystatin C into creatinine containing equations improved the accuracy of the estimates of glomerular filtration rate in patients with moderate chronic kidney disease and reduced bias at higher levels of glomerular filtration rate." (PMID 41586348, 2026).
chronic kidney disease (continued). "The use of cystatin C modestly increases the economic cost of managing chronic kidney disease." (PMID 41586348, 2026). "Notably, a statistically significant decline in estimated glomerular filtration rate (eGFR), based on the Chronic Kidney Disease Epidemiology Collaboration (CKD-EPI) cystatin C formula (eGFRcysC), was observed in both female and male participants." (PMID 41200622, 2025). "Cystatin C has found widespread application in chronic kidney disease settings." (PMID 40141244, 2025). "Finally, three patients with known chronic kidney disease had elevated cystatin C, indicating impaired glomerular function." (PMID 40760494, 2025). "Moreover, using cystatin-C as a biomarker for chronic kidney disease (CKD) may yield more accurate risk estimates and offer enhanced prognostic value for cardiovascular events and overall mortality, especially in low-risk populations." (PMID 41221210, 2025). "Her cystatin C was 1.1 mg/L and calculated glomerular filtration rate was 56 mL/min/1.73 m2 (by CKiD U25 eGFR equation using creatinine and cystatin C), placing her in Stage 3 chronic renal failure (defined by a GFR between 30 and 59 mL/min/1.73 m2)." (PMID 40546339, 2025). "Our data suggest that both cystatin C-based formulas might perform better than the creatinine-based formulas in the detection of chronic kidney disease and worse in the diagnosis of hyperfiltration." (PMID 39792299, 2025). "Classically, cystatin C has proved to be useful in the setting of chronic kidney disease." (PMID 38166710, 2024). "eGFR is a common indicator based on serumcreatinine levels, age, sex and cystatin C (according to the 2012 Chronic Kidney Disease Epidemiology Collaboration (CKD-EPI)cystatin C equation), which is ideal for reflecting kidney function and isconsidered an alternative to GFR in clinical practice." (PMID 39077336, 2024). "The equations used to estimate GFR using creatinine and cystatin c are derived from children with chronic kidney disease, and many of our subjects were of a young age, including less than 12 months of age, where their kidney function may still be evolving." (PMID 38172875, 2024). "Therefore, many candidate substances, such as NGAL, KIM-1, and cystatin C, have been suggested as markers of the early stage of acute kidney injury and chronic kidney disease, and their pathological mechanisms have been studied." (PMID 39199847, 2024). "The three most common equations for estimating GFR include the bedside Schwartz equation based on Creatinine, Cystatin-C based equation, Creatinine-Cystatin C-based Chronic Kidney Disease in Children (CKiD) equation, and U25 modification for CKiD equation for patients under 25 years old." (PMID 37287918, 2023). "Moreover, creatinine-based eGFR is less accurate in patients with lower GFR or chronic kidney disease, and thus utilizing both cystatin c, and creatinine has been strongly suggested to accurately determine renal function in these patients." (PMID 36997837, 2023). "The findings of this study suggest that, in the absence of cystatin C testing, estimated glomerular filtration rate inadequately distinguishes the broader risks associated with mild chronic kidney disease based on serum creatinine level." (PMID 36282503, 2022). "Although cystatin C can be more expensive to measure, there is evidence that eGFR measures incorporating cystatin C have improved accuracy for predicting outcomes such as death and end-stage renal disease." (PMID 34048360, 2021). "Patients with both serum creatinine eGFR and combined creatinine- and cystatin C-based eGFR < 60 mL/min/1.73 m2, had markedly elevated risks for death, coronary vascular disease, and end-stage renal disease endpoints compared to individuals with GFR > 60 mL/min/1.73 m2." (PMID 34943527, 2021). "Many studies have reported that Cystatin C is one of the early markers of chronic kidney disease which might serve as early and effective markers for cognitive decline in kidney patients." (PMID 33243163, 2020).
chronic kidney disease (continued). "Cystatin C is a well-validated marker of glomerular filtration rate in chronic kidney disease." (PMID 32653023, 2020). "Cystatin C is a well-validated marker of kidney function in chronic kidney disease and may be a superior marker of acute kidney injury leading to impaired GFR compared to serum creatinine among critically ill patients." (PMID 32653023, 2020). "Using the 90th percentiles of the CV values as a limit for clinical change means that the concentration of NGAL has to change by 83.3%, KIM1 by 45.5% and Cystatin C by 46.3% before the change can be considered clinically significant in patients with chronic kidney disease." (PMID 32349578, 2020). "Serum cystatin C level correlates with glomerular filtration rate, which is an important marker of kidney health and determinant of the progression of both diabetes and chronic kidney disease." (PMID 30775381, 2019). "However, a higher level of cystatin C was associated with sCr level >1.4 mg/dL, consistent with our previous finding that serum cystatin C concentration could detect partial recovery of kidney function and progression to chronic kidney disease in kidney donors." (PMID 31137470, 2019). "The present work aimed to study the agreement of a broad group of creatinine and/or cystatin-C based formulas with real renal function in a large population of diabetic patients over a wide range of GFR (from advanced chronic kidney disease (CKD) to hyperfiltration)." (PMID 31561432, 2019). "Cystatin C in serum is a biomarker of kidney function, and chronic kidney disease." (PMID 30134803, 2018). "In this cohort, the use of cystatin C did not result in improved risk prediction for all-cause mortality or progression of chronic kidney disease." (PMID 29016597, 2017). "On the other hand, elevated cystatin C is reportedly associated with the presence or likely development of cardiovascular disease in subjects without chronic kidney disease." (PMID 28922364, 2017). "•Cystatin C, a marker of chronic kidney disease (CKD), exists as multiple proteoforms." (PMID 36778895, 2016). "Future prospective trials will have to elucidate whether serum Ang-2 concentrations alone or in combination with serum cystatin C concentrations might improve the (early) diagnosis of kidney damage or serve as a prognostic marker for chronic renal failure." (PMID 27893762, 2016). "While often viewed as a marker of chronic kidney disease, Cystatin C (Cyst-C) may also reflect systemic inflammation." (PMID 25903849, 2015). "The aims of this study were to compare the predictive values of the Chronic Kidney Disease Epidemiology Collaboration (CKD-EPI)-creatinine, CKD-EPI-cystatin C and CKD-EPI-creatinine-cystatin C eGFR equations for all-cause mortality and CVD events (hospitalizations±mortality)." (PMID 25265151, 2014). "The present study aimed to establish reference intervals for serum cystatin C (Scys-C) stratified by stages of chronic kidney disease, explore factors influencing Scys-C and compare the performance of Scys-C with serum creatinine (Scr) in the young and elderly." (PMID 24465871, 2014). "First, we did not screen other measures of impaired kidney function, such as microalbuminuria or cystatin C. Microalbuminuria may be a better marker of early kidney dysfunction, and cystatin C may be a better marker of chronic kidney disease than creatinine." (PMID 23083001, 2012). "Recently, serum cystatin C-based equations, the newer creatinine formula (The Chronic Kidney Disease Epidemiology Collaboration formula (CKD-EPI)), and equation that use both serum creatinine and cystatin C (CKD-EPI creatinine & cystatin formula) were proposed as new GFR markers." (PMID 23008697, 2012). "Cystatin C may be a better marker of chronic kidney disease than creatinine and may be a better predictor for cardiovascular disease." (PMID 21311747, 2011).
chronic kidney disease (continued). "We will compare the accuracy of the following glomerular filtration rate measures with the reference measure: Modification of Diet in Renal Disease 4-variable formula, Chronic Kidney Disease Epidemiology Collaboration equation, Cockcroft-Gault formula and cystatin C- derived estimates." (PMID 20167129, 2010). "There are several possible explanations for the association of cystatin C with procoagulant and inflammatory biomarkers in patients without chronic kidney disease." (PMID 18681974, 2008). "Background/Objectives: Cystatin C-based and combined creatinine-cystatin C estimated glomerular filtration rate (eGFR) equations improve early chronic kidney disease (CKD) detection and prediction of adverse outcomes compared to creatinine alone." (PMID 42196857, 2026). "employed SHAP to identify serum cystatin C (SCysC) and serum creatinine (SCr) as the most critical indicators for classifying chronic kidney disease (CKD) stages, while factors such as blood pressure and CRP levels were less influential." (PMID 41403092, 2025). "Thus, in clinical routine, the addition of a cystatin C-based GFR estimation might be helpful to identify impaired renal function or chronic kidney disease in patients with diabetes mellitus." (PMID 39792299, 2025). "Evaluation of the renal function was performed in the two groups using the Chronic Kidney Disease Epidemiology Collaboration (CKD-Epi) algorithm, in which both creatinine and cystatin-C are included." (PMID 40563319, 2025). "Cystatin C is a low-molecular-weight protein freely filtered by the glomeruli and reabsorbed in the proximal tubules, making it a more reliable marker of eGFR than creatinine, particularly in individuals with altered muscle mass or those at early stages of chronic kidney disease (CKD)." (PMID 40978830, 2025). "Furthermore, our analysis may also have underestimated the effect of cadmium and lead exposure due to the known limitations of creatinine based eGFR as a marker of chronic kidney disease as compared to eGFR based on serum cystatin C." (PMID 38625896, 2024). "Increasing Apgar scores were associated with higher blood urea levels and with lower blood Cystatin C. Women with chronic kidney disease (CKD) showed an increase in the number of babies born with low Apgar scores." (PMID 39189174, 2024). "Some of them are based on cystatin C values, of which the most commonly used is the CKD-EPI CyC (Chronic Kidney Disease Epidemiology Collaboration)." (PMID 36983618, 2023). "In the adjusted logistic regression analyses, the highest cystatin C level and ln-transformed cystatin C levels were independently associated with the risks of developing severe COVID-19 and all-cause mortality in overall patients or patients without chronic kidney disease (values < 0.05)." (PMID 37593314, 2023). "Additionally, in those patients with chronic kidney diseases (CKD) of different causes sUromod levels can reflect the tubular function but also other renal parameters, correlating with serum creatinine, blood urea nitrogen and cystatin C." (PMID 36301848, 2022). "The estimated GFR (eGFR), calculated using a combination of age, sex, race, and serum levels of creatinine and/or cystatin C, is convenient and useful for screen chronic kidney disease (CKD)." (PMID 34934934, 2022). "A study conducted in the United Kingdom demonstrated that serum concentrations of free light chains increased progressively with chronic kidney disease (CKD) stage and also correlated strongly with renal function tests including cystatin C." (PMID 36992723, 2022). "The patients with chronic kidney disease (CKD) were defined as having an estimated glomerular filtration rate (eGFR) CKD-EPI Cr-Cystatin C < 60 ml/min/1.73 m2." (PMID 35308546, 2022).